ADAM28 (ADAM metallopeptidase domain 28)
Description:
May play a role in the adhesive and proteolytic events that occur during lymphocyte emigration or may function in ectodomain shedding of lymphocyte surface target proteins, such as FASL and CD40L. May be involved in sperm maturation.
Synonyms: ADAM 28; eMDC II; MDC-L; ADAM23; MDCL; eMDCII; MDC-Lm; MDC-Ls
Tractability: Antibody: its Gene Ontology location is reachable by antibodies, with high confidence; UniProt places it where antibodies can reach, with medium confidence; UniProt predicts a signal peptide or a membrane-spanning region. PROTAC: its protein half-life has been measured.
Gene: Protein-coding gene on chromosome 8 (24,294,016 to 24,359,014, forward strand). Ensembl gene ENSG00000042980.
Subcellular location: Cell membrane (Isoform 1); Secreted (Isoform 2)
Subcellular location (Human Protein Atlas): Plasma membrane; Mitochondria; Predicted to be secreted
Gene Ontology:
Molecular function: immunoglobulin receptor binding; metallopeptidase activity; protein binding; metalloendopeptidase activity
Biological process: proteolysis; spermatogenesis
Cellular component: plasma membrane; cell surface; extracellular region
Genetic constraint (gnomAD): Loss-of-function variants: 73 observed, 72.11 expected, observed/expected ratio (o/e) 1.01, 90% interval 0.84 to 1.23. The upper end of that interval is the gene's LOEUF score, 1.23, which puts it in group 5 of 6, group 1 being the genes least tolerant of losing a copy. Missense variants: 812 observed, 788.65 expected, observed/expected ratio (o/e) 1.03, 90% interval 0.97 to 1.09. Synonymous variants: 270 observed, 261.26 expected, observed/expected ratio (o/e) 1.03, 90% interval 0.94 to 1.14.
Homologues: Orthologues: chimpanzee ADAM28 (98% identical), macaque ADAM28 (90% identical), dog ADAM28 (81% identical), rabbit ADAM28 (81% identical), pig ADAM28 (76% identical), mouse Adam28 (70% identical), rat Adam28 (67% identical), guinea pig ADAM28 (65% identical), zebrafish adam28 (42% identical), tropical clawed frog adam28 (41% identical), tropical clawed frog adam28.2 (39% identical), Drosophila melanogaster kuz (18% identical), and 1 more. Paralogues in human: ADAM8 (35% identical), ADAM7 (35% identical), ADAM19 (32% identical), ADAM12 (31% identical), ADAM33 (30% identical), ADAM9 (30% identical), ADAM15 (29% identical), ADAMDEC1 (26% identical), ADAM23 (26% identical), ADAM22 (25% identical), ADAM11 (25% identical), ADAM20 (25% identical), and 8 more.
Diseases named in the same sentence as ADAM28 in open-access papers:
ADAM28 is named in the same sentence as 49 diseases in open-access papers, as found by Europe PMC text mining. Sharing a sentence is not in itself a finding about the gene and the disease. The quoted sentences say what the papers report.
breast carcinoma (6 papers, 2016 to 2022). "For instance, we found that TSHZ2 over-expression in MCF-7 cells suppressed the expression of genes such as ADAM28, which was reported to impact on the breast cancer biology (see GSE64351 for the details)." (PMID 26744317, 2016). "A pronounced expression of ADAM28 was frequently observed in human solid tumors, such as lung cancer, breast cancer and bladder cancer." (PMID 27661126, 2016). "Accumulated lines of evidence have shown that ADAM28 expression was strikingly up-regulated in several human cancers, such as non-small cell lung cancer, breast cancer, bladder cancer and chronic lymphocytic leukemia." (PMID 27661126, 2016). "The aggressive MDA-MB-231 breast cancer cells have been shown to express higher levels of ADAM28 and demonstrate resistance to VWF-induced apoptosis, whereas the less aggressive MCF7 breast cancer cells have been found to express lower levels of ADAM28 and are susceptible to apoptosis." (PMID 33571850, 2021). "The presence of CD20+CD22+ADAM28+ B cells in the TLSs was verified in multiple types of cancers, including colorectal cancer (CRC), breast cancer, skin squamous cell cancer (SCC), and renal clear cell cancer (RCC)." (PMID 35634306, 2022).
lung carcinoma (5 papers, 2015 to 2022). "More recently, it was found that aggressive breast and lung cancer cells with high levels of ADAM28 (a disintegrin and metalloproteinase 28) are able to avoid VWF-induced apoptosis at micrometastatic sites." (PMID 25846632, 2015). "With respect to lung carcinomas, the expression of ADAM28 was also elevated, suggesting that it may be a better serological and immunohistochemical marker for non-small-cell lung cancers (NSCLC)." (PMID 27661126, 2016). "Interestingly, a previous study of lung cancer showed that ADAM28 can downregulate vWF and cleave proapoptotic VWF in carcinoma cells, thereby increasing lung metastasis." (PMID 25886574, 2015). "For instance, ADAM28 was the most frequent and selective ADAM species expressing in the breast and lung carcinoma tissues, and the abundance of its transcripts was directly correlated with the capacity of cell proliferation and metastasis." (PMID 27661126, 2016).
colorectal cancer (4 papers, 2016 to 2022). A primary or metastatic malignant neoplasm that affects the colon or rectum. "The analysis showed that serum levels of ADAM10 and ADAM28 are significantly higher in patients with colorectal cancer and correlate with histopathological grading and with presence of distant metastases." (PMID 31565100, 2019). "However, the role of ADAM28 in colorectal cancer remains controversial." (PMID 28430139, 2017).
non-small cell lung carcinoma (4 papers, 2016 to 2022). A group of at least three distinct histological types of lung cancer, including non-small cell squamous cell carcinoma, adenocarcinoma, and large cell carcinoma. "Recently, it was suggested that ADAM28 might play a role in key immunomodulatory mechanisms since CD20+/CD22+/ADAM28+ B cells were shown to promote response to immune checkpoint inhibitor therapy in non-small-cell lung cancer." (PMID 36685493, 2022). "Overexpression of ADAM28 by carcinoma cells has been described in a wide range of cancers including breast cancer, chondrosarcoma, head and neck carcinoma, B-cell acute lymphoblastic leukemia, bladder carcinoma, non-small cell lung carcinoma (NSCLC) and prostate cancer." (PMID 30647853, 2018).
metabolic syndrome (3 papers, 2017 to 2021). A cluster of metabolic risk factors for CARDIOVASCULAR DISEASES and TYPE 2 DIABETES MELLITUS. "In this study, we establish that ADAM28 is pathogenic in the metabolic syndrome and provide evidence that metalloproteinase inhibition is a potential therapeutic target for anti-obesity agents." (PMID 28430139, 2017). "Here, we provide evidence to show in our current functional study that ADAM28 appears to also play a pathogenic role in the metabolic syndrome." (PMID 28430139, 2017). "Our novel findings show that increased ADAM28 mRNA and protein expression in high fat diet-induced obesity is associated with promoting features of the metabolic syndrome in mice." (PMID 28430139, 2017). "The results of this study provide important insights into the pathogenic role of the metalloproteinase ADAM28 in the metabolic syndrome and suggests that downregulation of ADAM28 may be a potential therapeutic strategy in the metabolic syndrome." (PMID 28430139, 2017). "Therefore, our current data further supports ADAM28’s pathogenic role in the metabolic syndrome." (PMID 28430139, 2017). "It is highly likely that ADAM17, ADAM19 and ADAM28 work in concert to promote the metabolic syndrome." (PMID 33904577, 2021). "We showed for the first time in humans that both ADAM19 and ADAM28 are strongly correlated with parameters of the metabolic syndrome, particularly BMI, relative fat and the index of insulin resistance (HOMA-IR)." (PMID 33904577, 2021). "It was established that the expression of ADAM28 was significantly higher in mice with the metabolic syndrome compared to a healthy group." (PMID 31565100, 2019). "Our novel study characterised the expression of ADAM28 in mice with the metabolic syndrome and used molecular inhibition approaches to investigate the functional role of ADAM28 in the pathogenesis of high fat diet-induced obesity." (PMID 28430139, 2017). "In our current study, we aimed to translate our previous findings into an in vivo animal model to assess the effects of limiting ADAM28 activity on parameters of the metabolic syndrome." (PMID 28430139, 2017). "We identified that ADAM28 mRNA and protein expression was markedly increased in the livers of mice with the metabolic syndrome." (PMID 28430139, 2017). "For the first time, we have examined the role of ADAM28 in the metabolic syndrome in an in vivo mouse model." (PMID 28430139, 2017). "Our previous work and that from other groups have reported that ADAM28 is elevated in overweight and obese humans and correlates with several parameters of the metabolic syndrome." (PMID 28430139, 2017). "Our group has previously sought to ascertain whether the metalloproteinases ADAM19 and ADAM28 correlate with parameters of the metabolic syndrome in mice and humans." (PMID 33904577, 2021). "We have previously reported that high expression of ADAM28 mRNA in peripheral blood mononuclear cells from the San Antonio Family Heart Study (SAFHS) cohort (n = 1240) correlated strongly with parameters of the metabolic syndrome." (PMID 28430139, 2017). "Our recent studies have confirmed that human ADAM28 is a novel sheddase of human TNF-α and reinforced the notion that ADAM28 is a novel sheddase of one of the major pro-inflammatory cytokines involved in the pathogenesis of the metabolic syndrome." (PMID 28430139, 2017). "After considering our previous metabolic studies with regards to ADAM19 and ADAM28 and the fact that ADAM17 plays a multitude of roles in the pathogenesis of many diseases, it is vital to further understand the role ADAM17 plays in promoting features of the metabolic syndrome." (PMID 33904577, 2021).
metastatic tumors (3 papers, 2012 to 2025). "While ADAMTS13 levels decrease in a range of disseminated cancers, ADAM28 expression is increased with advanced metastatic disease, likely due to a local tumor-induced expression of ADAM28." (PMID 35327035, 2022). "They found that ADAM8 was expressed significantly higher in metastatic tumors as well as identifying several proteinases of the ADAM-family (ADAM9, ADAM17, ADAM28, ADAMTS1, ADAMTS8 and ADAMTS15) -including ADAM8- which are HNSCC associated." (PMID 22369429, 2012). "ADAM28+ fibroblasts were enriched in precancerous and adjacent normal tissues but exhibited a marked decrease in primary and metastatic tumors." (PMID 41246350, 2025).
Type 2 diabetes (3 papers, 2007 to 2017). "The current study builds upon our previous association studies highlighting that A Disintegrin And Metalloproteinase 28 (ADAM28) appears to be implicated in the pathogenesis of obesity and type 2 diabetes in humans." (PMID 28430139, 2017). "Type 2 diabetes LDL also induced a significant increase in ADAM28 gene expression." (PMID 17714581, 2007). "In vitro, Type 2 diabetes LDL promoted the expression of the MMP-1, MMP-9, ADAM28, ADAM17 and ADAM15 genes compared to control LDL." (PMID 17714581, 2007).
acute lymphoblastic leukemia (2 papers, 2018 to 2025). Leukemia with an acute onset, characterized by the presence of lymphoblasts in the bone marrow and the peripheral blood. "ADAM28 could contribute to leukocyte transmigration by binding α4β1 and α4β7 integrins and is overexpressed in lymphoblastic leukemia." (PMID 30647853, 2018).
bladder cancer (2 papers, 2016 to 2022). "In bladder cancers, ADAM28 may represent a possible biomarker, since it is overexpressed in bladder transitional cell carcinoma patients and detected in urine." (PMID 35806060, 2022).
breast tumor (2 papers, 2016 to 2018). "Genetically engineered-mice fully deficient for ADAM28 unexpectedly display increased lung colonization by pulmonary, melanoma or breast tumor cells." (PMID 30647853, 2018). "For example, ADAM28 was overexpressed in human breast tumor tissues, which was positively correlated with the proliferative activity of the cancer cells." (PMID 27661126, 2016).
chronic lymphatic leukaemia (2 papers, 2017 to 2022). "ADAM28 has previously been shown to be responsible for sCD200 release in chronic lymphocytic leukemia." (PMID 36074574, 2022).
colon carcinoma (2 papers, 2016 to 2017). "miR-552 promotes the migration of colon cancer cells by targeting ADAM28 and miR-9 inhibits colon cancer cell migration and invasion by downregulating TM4SF1." (PMID 28725241, 2017).
liver cancer (2 papers, 2021 to 2023). An epithelial or non-epithelial malignant neoplasm that arises from the liver. "However, proliferation of liver cancer cells was inhibited by miR-574-3p through ADAM28 targeting thereby suggesting that ADAM28 promotes liver cancer." (PMID 33805340, 2021).
melanoma (2 papers, 2013 to 2018). A malignant, usually aggressive tumor composed of atypical, neoplastic melanocytes. "The increased tumor cell dissemination to lung parenchyma of ADAM28 KO mice was also demonstrated with B16K1 melanoma cells (**p<0.01)." (PMID 30647853, 2018). "Surprisingly, ADAM28 deletion resulted in an increased metastatic colonization of lung tissues after intravenous injection of pulmonary LLC, melanoma B16K1 or mammary 4T1 cells." (PMID 30647853, 2018).
Obesity (2 papers, 2017 to 2021). Accumulation of substantial excess body fat. "To further our previously published findings, we conducted ADAM28 expression and functional studies in our murine high fat diet-induced obesity model." (PMID 28430139, 2017). "Our next aim was therefore to utilise siRNA targeting mouse ADAM28 to reduce ADAM28 expression in vivo in our high fat diet-induced obesity mouse model." (PMID 28430139, 2017). "Therefore, neutralisation of ADAM19 and ADAM28 may be a potential therapeutic approach to treat obesity and T2D." (PMID 33904577, 2021).
pancreatic cancer (2 papers, 2021 to 2023). "The overexpression of ADAM28 in pancreatic cancer is closely related to the regulation of gemcitabine resistance, so it is a new prognostic biomarker in pancreatic cancer." (PMID 34007269, 2021). "In addition to protein levels, NSD3 induces global H3K36 dimethylation in pancreatic cancer cells and influences the mRNA levels for genes including ADAM28, ADAM9, BIRC3, CXCL5, DUOX2, GABRP, ITGB6, and RAB11FIP1." (PMID 37062069, 2023).
prostate carcinoma (2 papers, 2017 to 2022). A carcinoma that arises from epithelial cells of the prostate gland. "Of all the genes identified, only BRCA2 and ADAM28 have been previously classified as recurrently mutated drivers in prostate cancer." (PMID 36131292, 2022).
asthma (1 paper, 2022). "In this article, we establish a strong relationship between the expression of ADAM28 and asthma-associated bronchial hyperresponsiveness and remodelling." (PMID 36685493, 2022). "We report here that total ADAM28 expression in lungs is lower after allergen exposure in a mouse model of asthma." (PMID 36685493, 2022). "The exact mechanisms linking ADAM28 and a modulation of airway remodelling and responsiveness in asthma are still to be unveiled but there are arguments to hypothesize that ADAM28 contributes to the events leading to the asthma phenotype." (PMID 36685493, 2022). "These parameters are closely related to the remodelling classically observed in models of asthma after 90 days allergen exposure therefore confirming our histological observations (lower airway remodelling in ADAM28-/- mice as compared to ADAM28+/+ after OVA exposure)." (PMID 36685493, 2022). "Although its precise biological functions are still uncertain, ADAM28 might play a role in key mechanisms leading to asthma-related inflammation and airway remodelling." (PMID 36685493, 2022). "In order to assess ADAM28 expression in lung in mouse models mimicking acute to chronic features of asthma, mRNAs corresponding to total ADAM28, soluble form (referred to as Variant 4: Var4) and membrane-bound form (or Variant 1: Var1) were measured by RT-PCR after ST, IT and LT allergen exposure." (PMID 36685493, 2022). "Interestingly, ADAM28 might activate pathways leading to or supporting asthma-related inflammation by modulating the biological activity of mediators as TNF-α." (PMID 36685493, 2022). "As our working hypothesis was that ADAM28 could play a role in asthma-related airway remodelling, we focused on a long term allergen-exposure model (LT) obtained after 90 days of exposure to allergens where the highest levels of ADAM28 expression in the lung tissue were measured." (PMID 36685493, 2022). "ADAM28 (a disintegrin and metalloproteinase 28) might play a role in asthma pathophysiology." (PMID 36685493, 2022). "Furthermore, our observations suggest that ADAM28 contributes to mechanisms leading to asthma-related airway inflammation and remodelling but it is probably not the final effector and further experiments are needed to fully unveil the precise molecular mechanism." (PMID 36685493, 2022).
Burkitt lymphoma (1 paper, 2016). A rare form of malignant mature B-cell non-Hodgkin lymphoma. "In order to recapitulate the repression of ADAM28 a similar approach was used in the EBV-negative Burkitt’s lymphoma cell line DG75, here luciferase activity of the ADAM28 construct was robust." (PMID 26751214, 2016).
chronic asthma (1 paper, 2022). An asthma that is characterized by the development of persistent airway inflammation and recurrent attacks of breathlessness and wheezing, which vary in severity and frequency. "Notably, microarray studies show an upregulation of ADAM28 expression after induction of lung inflammation in a mouse model of chronic asthma and ADAM28 is expressed by airway epithelial cells." (PMID 36685493, 2022).
Infertility (1 paper, 2024). "Mice lacking Ovch2 or Adam28 possess abnormal sperm maturation and complete infertility or reduced male fertility, respectively." (PMID 38169386, 2024).
lentivirus infection (1 paper, 2017). Virus diseases caused by the Lentivirus genus. "ADAM28 overexpression but not control lentivirus infection induced CD19‐deficient MZP (CD21hiIgMhiCD1dhiCD23+IgDhi) to produce MZ B cells (CD21hiIgMhiCD1dhiCD23−IgDlo)." (PMID 28707394, 2017).
lung adenocarcinoma (1 paper, 2016). A carcinoma that arises from the lung and is characterized by the presence of malignant glandular epithelial cells. "In asbestos-related lung adenocarcinomas, however the expression of ADAM28 was even more elevated than non-asbestos related lung cancer adenocarcinoma." (PMID 27661126, 2016).
lymph node metastasis (1 paper, 2016). "Intriguingly, such an evoked expression of ADAM28 was also found in the patients with recurrent NSCLC and/or lymph node metastasis, and was correlated with a poor disease-free survival." (PMID 27661126, 2016).
metastatic cancer (1 paper, 2021). A carcinoma which has spread from the original site of growth to another anatomic site. "While ADAM28 acts as a semi-functional homologue of ADAMTS-13 in cleaving circulating VWF, it is interesting to note that while ADAMTS-13 levels have been shown to decrease in a range of metastatic cancer including breast, ADAM28 expression is correlated with advanced disseminated disease." (PMID 33571850, 2021).
systemic lupus erythematosus (1 paper, 2022). An autoimmune multi-organ disease typically associated with vasculopathy and autoantibody production. "The close correlation between ADAMDEC1 and ADAM28 in systemic lupus erythematosus (SLE) regulates the disease inflammatory process." (PMID 35514959, 2022).
uterine infection (1 paper, 2009). "The uterine infection was also associated with a marked upregulation of several ADAM and ADAMTS metalloproteases, primarily ADAMTS2, ADAMTS5, ADAMDEC1 and ADAM28." (PMID 19956711, 2009).